CRIPTO (cripto, EGF-CFC family member)
Diseases named in the same sentence as CRIPTO in open-access papers (continued):
Sharing a sentence is not in itself a finding about the gene and the disease.
tumor (18 papers, 2008 to 2025). "One intriguing possibility is that inflammatory infiltrating fibroblasts (and/or possibly macrophages) produce or respond to CRIPTO in the context of necrotic tumor regions and associated detritus or fibrosis." (PMID 34576327, 2021). "Overall, these observations indicate that CRIPTO expression identifies a dynamic population of lung CSCs that may be implicated in chemoresistance and post-chemotherapy tumor progression." (PMID 35719935, 2022). "CRIPTO has been implicated in multiple neoplastic settings, but how it orchestrates tumorigenesis and tumor progression remains unclear." (PMID 34576327, 2021). "Thus, through the induction of soluble angiogenic factors such as VEGF and governance of angiogenic phenotypes (whether acting on endothelial compartment or through vascular mimicry), CRIPTO expression in tumors could reflect tumor associated angiogenesis." (PMID 34576327, 2021). "Our study indicates that CRIPTO also influences the tumor microenvironment, particularly affecting invasiveness levels and leukocyte infiltration (data not shown) within the tumor stroma." (PMID 39592836, 2025). "Leveraging newly generated GEMM models, our results indicated that groups with CRIPTO knockout (“C”) exhibited a tendency towards a less aggressive tumor behavior." (PMID 39592836, 2025). "While in control conditions (N, NP, NPK), no significant changes were detected in the expression of cMYC targets, CRIPTO knockout correlates with decreased cMYC targets expression and tumor progression." (PMID 39592836, 2025). "Haematoxylin and eosin (H&E) and immunohistochemistry (IHC) stainings were performed, and analyzed cores showed CRIPTO expression was highest in tumor cells, which constituted a greater proportion of total cells compared to stromal cells." (PMID 39592836, 2025). "Taken together, our data highlights a role for CRIPTO in tumor invasiveness and progression, which carries implications for biomarkers and targeted therapies." (PMID 39592836, 2025). "CRIPTO’s potent influence on extravasation dynamics further underscores its correlation with tumor cell aggressiveness." (PMID 39592836, 2025). "GRP78 also plays a significant role in promoting tumor growth and metastasis, including through interactions with CRIPTO or CDK7." (PMID 40223122, 2025). "CRIPTO (or CR-1 or TDGF1) is a protein that plays an active role in tumor initiation and progression." (PMID 39592836, 2025). "Further studies will be needed to demonstrate a causal role of CRIPTO in NSCLC and in post-chemotherapy tumor cell repopulation." (PMID 35719935, 2022). "We analyzed the levels of cyclin E (as a marker of cell proliferation) and of CRIPTO in tumor xenografts harvested at different times of treatment, i.e. after the first week of treatment, at treatment stop and after three additional weeks of tumor growth." (PMID 35719935, 2022). "In NSCLC tumor xenografts, chemotherapeutic agents induced partial cell death and tumor stabilization followed by CRIPTO overexpression and tumor progression." (PMID 35719935, 2022). "Chemotherapy treatment of NSCLC spheroids and xenografts increased CRIPTO expression and enhanced tumor progression in vivo as compared to untreated tumors." (PMID 35719935, 2022). "Altogether, these findings highlight a complex role of CRIPTO in regulating tumor stemness that deserves further investigation, also in light of potential CRIPTO targeting by molecular and immunotherapeutic strategies." (PMID 35719935, 2022). "And, it has never been determined how much (quantitatively) CRIPTO is required for adaptive responses in normal or tumor tissues, much less how much CRIPTO activity is needed." (PMID 34576327, 2021). "Despite increased protein levels and in vivo data supporting the role of CRIPTO in tumorigenesis and progression, expression of CRIPTO has been particularly difficult to detect at the RNA level in both bulk and single-cell RNA-sequencing tumor data sets." (PMID 34576327, 2021).
tumor (continued). "An in-depth study of local ligand concentrations in various tumor microenvironments as they impact CRIPTO-regulated signaling would likely also be illuminating." (PMID 34576327, 2021). "Subsequent inhibition of CRIPTO in these xenograft tumors reduces proliferative capacity specifically in cells with high levels of HIF1α, supporting the notion that CRIPTO signaling is necessary for tumor growth in hypoxic domains." (PMID 34576327, 2021). "CRIPTO has also been targeted by inhibitory monoclonal antibodies which decrease primary tumor volume in testicular and colonic xenograft models." (PMID 34576327, 2021). "Potential paracrine regulation of CRIPTO, for instance to govern this EMT/MET duality, is likely to be multifactorial, reflecting different pools of effectors and differeing receptiveness of tumor cells to CRIPTO pathway activation." (PMID 34576327, 2021). "Despite the remaining challenges, recent advances have strengthened our interest and enthusiasm for eyeing CRIPTO as a viable therapeutic target in diverse neoplasms and inflammatory conditions." (PMID 34576327, 2021). "More recent work showed that despite correlating with primary tumor burden, soluble CRIPTO was unable to confer resistance to Osimertinib, a 3rd generation EGFR-TKI, in NSCLC." (PMID 34576327, 2021). "Recently, we (BTS) showed within MDA-MB-231 xenograft tumors that CRIPTO immunoreactivity localizes to tumor microdomains exhibiting hallmarks of stress such as hypoxia." (PMID 34576327, 2021). "Administration of mCr-1 plasmid DNA generated an immune response against CRIPTO, which subsequently reduced primary tumor volume and significantly impaired metastatic burden." (PMID 34576327, 2021). "EGFR-TKI therapy combined with a Src inhibitor produces a synergistic antitumor effect against CRIPTO positive/EGFR-mutant xenograft tumor models." (PMID 34568058, 2021). "Evidence shows that proliferation, migration, and invasion are enhanced by CRIPTO, properties that have also been shown to stimulate tumor angiogenesis." (PMID 34576327, 2021). "The AKT pathway is a critical regulator of tumor cell growth and stem cell-like properties, and our results suggest that blocking this aspect of CRIPTO signaling plays a key role in inhibiting maintenance of the stem cell phenotype and oncogenesis." (PMID 33187540, 2020). "As has been found for other neoplasms, we previously showed, in a small set of samples, that CRIPTO is detectable in serum of TGCT patients." (PMID 32210110, 2020). "Several groups are seeking to develop CRIPTO as a biomarker of tumor aggressiveness and validate therapeutic modalities directed at blocking CRIPTO-induced oncogenesis." (PMID 33187540, 2020). "Consistent with our observations in vitro, these in vivo data indicate that CRIPTO signaling is required for tumor cell proliferation under conditions of stress and that this stress-adaptation signaling can be blocked with ALK4L75A-Fc." (PMID 33187540, 2020). "Based on the findings presented here, we propose that re-localization of GRP78 to the cell surface during stressful conditions enhances CRIPTO signaling and thereby promotes cellular plasticity, adaptation to stress, and tumor progression." (PMID 33187540, 2020). "In depth, function annotation sub-categories significantly enriched in genes involved in the network and including CRIPTO, were: cell migration, proliferation of tumor cells, cell differentiation, and blood vessel development." (PMID 25629528, 2015). "Numerous studies have demonstrated correlation between high expression levels of CRIPTO and malignant transformation, tumor invasiveness, metastatic spreading and hence poor prognosis." (PMID 25629528, 2015). "As other GPI linked proteins such as the carcinoembryonic antigen (CEA), one of the most used tumor markers, CRIPTO is able to reach the bloodstream." (PMID 25629528, 2015).
tumor (continued). "In both studies, tumor tissues and patient-matched blood samples have been analyzed, showing that CRIPTO high levels in the plasma correspond to re-expression of CRIPTO in tumor tissues." (PMID 25629528, 2015). "Among these tumor cells, a high/low percentage of CRIPTO-positive tumor cells were identified." (PMID 39592836, 2025). "CRIPTO levels showed a slightly different trend, as they started to raise shortly after treatment start and progressively increased at treatment stop and during tumor progression." (PMID 35719935, 2022). "The increase of CRIPTO expression mirrored chemotherapy-induced tumor progression in NSCLC xenografts and may reflect a selective survival of chemoresistant CSCs." (PMID 35719935, 2022). "Our results suggest a novel localization and function for CRIPTO in large EVs, and give precious hints for the development of novel therapeutic approaches, based on the control of tumor cell migration, to ultimately improve prognosis and quality of life of GBM patients." (PMID 35954365, 2022). "It is also tempting to speculate in this regard that hypoxia secondary to tumor cell proliferation is the principal CRIPTO inductive cue." (PMID 34576327, 2021). "Through an exosome mediated mechanism, CRIPTO might promote mesenchymal traits within discrete tumor domains, while simultaneously priming pre-metastatic niches at distant sites through long range vesicle transfer." (PMID 34576327, 2021). "Given the heterogeneity of CRIPTO expression in various tissues, it is interesting to postulate whether CRIPTO expression delineates different classes of CAFs and may explain their tumor-promoting capacity." (PMID 34576327, 2021). "Whether soluble CRIPTO has a functional role in treatment response or simply tracks with tumor burden is still debated." (PMID 34576327, 2021). "In either case, reversing CRIPTO may mediated EMT induction may be especially advantageous as mesenchymal phenotypes appear to contribute to multiple steps in tumor cell dissemination as well as therapy resistance." (PMID 34576327, 2021). "Whether serum CRIPTO can serve as a biomarker for tumor burden in patients with NSCLC deserves further investigation." (PMID 34568058, 2021). "Whether CRIPTO promotes EMT in multiple subpopulations within a tumor or a single population is unknown." (PMID 34576327, 2021). "In fact, while CRIPTOhigh cells shortly returned to baseline CRIPTO levels and proliferation state, CRIPTOlow cells reacted to the perturbation with a strong increase of CRIPTO RNA and a corresponding proliferative burst observed both in tumor spheroids and xenografts." (PMID 35719935, 2022). "In a more general scenario, EV-CRIPTO might interfere with the activity of the other CRIPTO forms (the plasma membrane bound and the soluble ones), and the balance among the different CRIPTO forms might account for the resultant effect of CRIPTO as a tumor agonist or antagonist." (PMID 35954365, 2022). "Furthermore, our results showed that CRIPTO is involved in NSCLC CSCs plasticity, as separation of CRIPTOhigh and CRIPTOlow cells resulted in a rapid modification of CRIPTO levels in the two subpopulations and in a functional response in terms of tumor cell expansion." (PMID 35719935, 2022). "CRIPTO’s role in fibrosis may similarly provide survival and growth promoting cytokine pools while simultaneously providing a physical collagen tract that facilitate tumor cell dissemination." (PMID 34576327, 2021). "Furthermore, hypoxic conditions within these tumor regions may also influence local CRIPTO production as a function of HIF1α binding to hypoxia response elements (HREs) within the CRIPTO promoter." (PMID 34576327, 2021). "Indeed, through its impact on stromal cell function, CRIPTO may be able to promote tumor progression through field effects involving ’s tumor several modes of tumor remodeling." (PMID 34576327, 2021).
tumor (continued). "Nevertheless, morphological and functional heterogeneity is a well-established and clinically challenging feature of most tumors and mounting evidence indicates that CRIPTO could be of particular importance in determining the phenotypes of specific subsets of tumor cells." (PMID 34576327, 2021). "In this regard, it is unclear whether CRIPTO’s well known effects on EMT are synonymous with its promotion of stemness, or whether they represent a separate mechanism by which CRIPTO can promote plasticity and intratumoral heterogeneity to impact tumor progression and treatment resistance." (PMID 34576327, 2021). "Our results showed that the organoid-forming efficiency significantly correlates with tumor progression (N vs. NPK, *p = 0.03) and CRIPTO expression." (PMID 39592836, 2025). "On the other side, CRIPTO is also able to induce many tumorigenic features, such as Epithelial-Mesenchymal transition (EMT), tumor cell proliferation, migration, and tumor neovascularization." (PMID 35954365, 2022). "CRIPTO desensitizes EGFR-mutant NSCLC tumor cells to EGFR-TKI treatment through CRIPTO-mediated Src activation, and inhibition of Src resensitizes CRIPTO-expressing cells to EGFR-TKI treatment." (PMID 34568058, 2021). "CRIPTO-1 is a member of the epidermal growth factor-CRIPTO-1/FRL-1/Cryptic (EGF/CFC) family, abundantly expressed in embryonic stem cells and tumor cells." (PMID 25165718, 2014). "While not reaching statistical significance, a slight increase in the mean % of cMYC positive cells was observed according to the state of tumor progression and was decreased in the absence of CRIPTO." (PMID 39592836, 2025). "Alternatively, there may be temporal dependency between hypoxia and stress induced CRIPTO that explain how CRIPTO can promote aggressive stem cell or EMT phenotypes, prior to subsequent invasion of vessels that enable tumor cell escape." (PMID 34576327, 2021). "In neoplastic settings, transcriptional regulators of CRIPTO do not necessarily represent discrete tumor suppressing or tumor promoting phenotypes." (PMID 34576327, 2021). "Although it is known that such tumor microdomains include both xenografted tumor cells and infiltrating host stroma, it is not yet clear which cells are signaling to which other cells through the agency of CRIPTO." (PMID 34576327, 2021). "Indeed, immune detection of CRIPTO and GRP78 in tumor xenografts showed robust staining for both CRIPTO and GRP78 at the cell periphery specifically in regions we previously identified as nutrient deprived." (PMID 33187540, 2020). "Cell populations positive and negative for CRIPTO expression were interconvertible, and interfering with their reciprocal equilibrium resulted in altered homeostasis of cell expansion both in spheroid cultures and in tumor xenografts." (PMID 35719935, 2022). "At the cellular level, sulforaphane decreased tumor-sphere formation in vitro and also reduced primary tumor volume in a TNBC xenograft model, however, these effects were somewhat modest, in contrast to the significant reduction in spontaneous lung metastasis observed following CRIPTO knockdown." (PMID 34576327, 2021). "Similarly, we find that targeting CRIPTO signaling with ALK4L75A-Fc specifically impacts cell proliferation in stressed microenvironments in tumors and inhibits metastasis, a process that requires tumor cells to adapt to multiple novel and stressful environments." (PMID 33187540, 2020).
CRIPTO also shares sentences with these, for which no sentence is quoted: adenocarcinoma (2 papers); esophageal squamous cell carcinoma (2); cholangitis (1); cutaneous melanoma (1); Duchenne muscular dystrophy (1); heart defects (1); invasive carcinoma (1); lung carcinoma (1); melanoma (1); nasopharyngeal carcinoma (1); prostate adenocarcinoma (1); testicular embryonic carcinoma (1); testicular tumors (1); triple-negative breast carcinoma (1); viral hepatitis (1).